CD4 (CD4 molecule)
Diseases named in the same sentence as CD4 in open-access papers (continued):
Sharing a sentence is not in itself a finding about the gene and the disease.
infection (continued). "Next, we wished to determine whether the early differential expansion of CD4+ and CD8+ T cells subsets by high and low dose L. major infection, respectively, is transient and related to differences in parasite burden at the infection site." (PMID 25412267, 2014). "Although studies of uncircumcised men document increased risk of natural HIV acquisition due to a high frequency of CD4+CCR5+ target cells in the foreskin, how this relates their Ad5 sero-positivity and titre levels with infection risk is not very clear." (PMID 25202303, 2014). "According to the proponents of the PAMP and Danger Models, most CD4 T cells, specific for peripheral self-antigens, are inactivated under steady-state conditions, when infections do not occur, or danger does not exist." (PMID 24684567, 2014). "Prior to infection, the number of CD4+ T cells in the MLN was not different in naive mice (day 0 postinfection) developmentally exposed to vehicle or TCDD." (PMID 25051576, 2014). "Central memory CD4+ and CD8+ T cells are largely located in the periphery of the LNs in close proximity to the lymphatic sinuses where a potential re-infection may occur." (PMID 25120547, 2014). "However, we and others have previously demonstrated that CD4+CD25+ Treg cells are preferentially infected with FIV and activated during FIV infection." (PMID 24438223, 2014). "Defining how HIV does, and does not, kill the host CD4 T cell that it infects is of paramount importance in an era when research is approaching a cure for infection." (PMID 26056587, 2014). "Both eYFP+ CD4+ T cells and ILC2 cells were detected in the lung during infection." (PMID 24586147, 2014). "Regarding the percentage of activated CD4+ T-cells in blood, an upward trend was observed in agreement with a previous report of an increase in the density of CD38 on CD4+ cells in blood during early infection." (PMID 25465205, 2014). "However, it must also be noted that CD4+ T cells and CD8+ T cells have antagonistic functions during infection." (PMID 24587276, 2014). "This was previously attributed to the protective action of EBOV-specific CD4+ and CD8+ T-cell response induced by these vaccines in limiting infection and the inability of KZ52 to completely block all entries of the EBOV into cells and its subsequent explosive replication." (PMID 25699183, 2014). "Our objective is to report CD4 decline and changes in viral load (VL) in a group of HIV-infected adults enrolled in a randomized trial of preventive treatment for TB in South Africa where clade C infection predominates." (PMID 24831447, 2014). "CD4+ T cells represent approximately 10% of the CX3CR1-GFP+ population at 7 weeks post-infection (data not shown)." (PMID 24967715, 2014). "Interestingly, within the same SHIV infected tissue, independent of the presence of HSV-2, the frequencies of migratory α4β7high CD4+ T cells and α4β7+ HLA-DR+ cells within the mucosa (left) strongly correlated with SHIV replication 3 days after infection." (PMID 25521298, 2014). "In contrast, a virus ablated in p8 and p12 expression (12KO) is poorly infectious in monocytes and CD4+T-cells in vitro, the infected cells are susceptible to CTL killing and infection is not sustained in vivo." (PMID 25375128, 2014). "Application of these models to both cell lines and activated primary CD4+ T-cells suggests that direct non-productive infections (latency) actually represent the majority of HIV-1 infections." (PMID 24502247, 2014). "CD4+ and CD8+ T cells are involved in modulation of infection and latency." (PMID 25276842, 2014). "The observation of a lack of a CD4+ cytokine response following secondary infection is consistent with the observation that IgA+ antibody secreting plasma cells also fail to boost after C. jejuni re-challenge." (PMID 25397604, 2014).
infection (continued). "Infection elicited an increase in specific IgA, IgG, and IgM antibodies and relative quantitative changes in several leukocyte populations, including CD3, CD4, CD8α, CD8β, MHC II, KuL01, and γδ TCR positive cells, both in the gastrointestinal tract and systemically." (PMID 26664914, 2014). "Collectively these data point to enhanced infection of DCs as a key trigger of the IL-10 induction cascade resulting in maintenance of elevated IL-10 expression in CD4 T cells and inhibition of LCMV-specific CD4 and CD8 T cell proliferation." (PMID 24613988, 2014). "Throughout this study LTNPs were defined as: HIV Patients with low viremia (<5000 copies/ml) that maintain a favourable course of infection (CD4 counts>350 cells/μl) over 5 years in the absence of therapy." (PMID 25369333, 2014). "The decreased surface expression of CD4, CXCR4, and CCR5 observed with ISD treatment may be an important factor in the blockade of de novo infection." (PMID 24827152, 2014). "CD4+ T cell counts and the known time of infection did not statistically differ between EC and CH (p = 0.298 and p = 0.722 respectively)." (PMID 25081906, 2014). "Preclinical trials in the SIV/macaques model demonstrate the induction of SIV-specific polyfunctional CD4+ and CD8+ T cell activity resulting in marked decreases in viral load using DNA or viral vector vaccine strategy as either post-infection therapy or prophylaxis against SIV." (PMID 24454311, 2014). "A reduction in infection by exosomos without CD4 was only detectable when HIV-1 Luc+ particles were pre-incubated with a high concentration of these exosomes, a concentration 20-fold higher than that found in conditioned culture media." (PMID 25423108, 2014). "In our cohort, 18.1% of the patients receiving cART had detectable viral loads, and 32% had a current CD4+ cell count below 350, indicating some degree of uncontrolled infection, due to either viral resistance or non-adherence." (PMID 24699873, 2014). "Prostratin, PMA and bryostatin-1 downregulate CD4 and CXCR4 and present mild anti-HIV activity, and ingenol-3-angelate has been shown to downregulate surface receptors blocking de novo infection." (PMID 24827152, 2014). "Thus, given the fact that IL-7 supports the emergence and survival of memory CD4+ and CD8+ T lymphocytes, the differential CD127 expression in the early stages of infection can be partly responsible for viral persistence." (PMID 24465502, 2014). "One subject evaluated in this re-infection model was protected from clinical illness upon re-infection, and interestingly, this subject shared similar CD4+ T cell profiles to study participants that were not protected from re-infection." (PMID 25397604, 2014). "The difference in CD4+ T-cell frequency between controllers and non-controllers became significant early after infection (8 and 12 weeks p.i.; P<0.05, Mann–Whitney test)." (PMID 24928910, 2014). "However, when the same mice were analyzed for their CD4+ and CD8+ T cell levels in blood, spleen, and draining lymph nodes, the impact of MusPV1 infection was much less pronounced." (PMID 25121947, 2014). "Since late stage R5 isolates are also more efficient at using low levels of CD4 and CCR5 for entry, it is possible that infection of naïve T-cells by late stage R5 Envs might contribute to the diminishment seen." (PMID 24957778, 2014). "CD4+ T-cell frequencies differed significantly soon after infection between controllers and non-controllers." (PMID 24928910, 2014). "PBMCs treated with prostratin and infected with HIV NL4-3-Luc pseudotyped with VSV envelope were not refractory to infection despite the downregulation of CD4 and CXCR4, confirming that the control of viral replication occurred at entry level." (PMID 24827152, 2014). "The Foxo1 inhibitor AS1842856 accelerated de novo viral gene expression and the sequella of infection, supporting the notion that HIV-1 suppression of Foxo1 activity may be a strategy to promote replication in resting CD4 T cells." (PMID 25330112, 2014).
infection (continued). "There were more CD38+ cells in the minor and severe infection groups than in the healthy and silent infection groups among CD4+ cells, but this difference was not statistically significant." (PMID 24646014, 2014). "At later stages of the infection animals with multi-bacillary lesions express predominantly a Th2-type immune response that is measured by the presence of MAP-specific IgG1 antibodies, production of which is driven by IL-4 or IL-10 producing CD4 T cells." (PMID 24415928, 2014). "We have demonstrated that the infection of primary CD4+ T cells, but not T cell lines, with HIV-1 results in an increased glycolytic flux." (PMID 25421745, 2014). "We observed a significant 2.5-fold increase in the IL10 transcript in sorted splenic CD4 T cells at day 250 after infection (P<0.05), with no changes in the expression of TGFB1." (PMID 24763747, 2014). "This resembles the phenotype of non-pathogenic infection in the natural hosts of SIV, such as African Green Monkeys and Sooty Mangabeys, in whom CD4 counts are maintained despite high levels of viremia, due to attenuated immune activation." (PMID 25161656, 2014). "Groups also did not statistically differ in their estimated duration of infection, CD4+ T cell counts, plasma or CSF HIV-1 RNA levels (p > 0.05 for all comparisons)." (PMID 25125210, 2014). "Furthermore, we compared the mRNA expression levels of CD45, CD4, CD8, and CD11b in the brains of WT and db/db mice at days 6 and 8 after infection using qRT-PCR." (PMID 24750819, 2014). "There were no significant changes in blood B cells, NK cells, γδ cells or CD4+/CD8+ ratio following infection in either of the groups (data not shown)." (PMID 24099891, 2014). "There is also strong evidence that mucosal HIV-specific CD8+ and CD4+ T cells modulate HIV-1 disease course, as they can control post-infection virus replication and persistence by directly killing infected target cells or secreting a number of antiviral cytokines." (PMID 24847327, 2014). "In contrast to the reported properties of peripheral blood derived Th22 cells without a characterised antigen specificity, IL-22 production in response to PA infection was from memory CD4+ T cells that did not express the skin-homing receptors CCR4 or CCR10." (PMID 24587305, 2014). "We have shown that whereas the proportion of circulating WC1+ γ/δ T-cells and CD14+ monocyte/macrophage cells did not change after PPRV infection of control goats, there was a decrease in the proportion of circulating CD4+ cells 4 days after challenge." (PMID 24568545, 2014). "Although primary CD4+ T-cells are considered to be the gold standard for HIV-1 latency models, we note a number of technical issues precluding the precise and unbiased evaluation of direct non-productive RGH infection in resting CD4+ T-cells." (PMID 24502247, 2014). "However, CD4+ T cell activation, as measured by expression of CD69, was higher in IN-inoculated mice than FP-inoculated mice throughout the course of infection and significantly greater 8 dpi." (PMID 24922480, 2014). "The affinity of gp120 for DC-SIGN is five times greater than for its cognate receptor CD4, suggesting that DC-SIGN on iDCs could be of particular importance when only few HIV-1 particles are present, such as in early infection." (PMID 25033082, 2014). "In this study, we investigated the outcome of a primary H. polygyrus infection in mice deficient in MyD88 signaling, and found that they were more resistant to infection than wild-type C57BL/6 mice and had a higher frequency of IL-4–producing CD4+ T cells following infection." (PMID 25114104, 2014). "According to the literature on cellular immune responses, CD4+ and CD8+ T cells as well as antibody-producing B cells make an important contribution to the control of influenza virus replication and virus clearance during infection." (PMID 24489827, 2014).
infection (continued). "Blood CD4+ T cells were significantly reduced at infection compared to baseline in the COPD group but not in the smokers." (PMID 24099891, 2014). "Interestingly, the percentage of double positive T cells (CD4+CD8+ T cells) in the thymus of LPi animals was significantly decreased (p<0.001) as a result of interaction between low protein diet and infection with L. infantum." (PMID 25535967, 2014). "This so-called trans-infection is particularly robust for mDCs and takes place at viral concentrations that do not allow for efficient infection of CD4+ T cells by cell-free virus." (PMID 25033082, 2014). "For lung cell composition, cigarette smoke exposure could not affect the number of total cells, macrophages, neutrophils, NK cells, CD4+ T cells and CD8+ T cells in the lung on day 5 after pdmH1N1 infection." (PMID 24465940, 2014). "Surprisingly, despite the strong activation of CD8+ T cells and their importance in primary immunity following low dose infection, secondary immunity in mice that healed their low dose L. major infection was completely dependent on CD4+ (and not CD8+) T cells." (PMID 25412267, 2014). "Among the subset of women aware of their HIV infection status, there was high reported engagement in HIV care, including CD4 staging and ART initiation; however large gaps in infection diagnosis resulted in low overall ART coverage among HIV-infected FSW trying to conceive." (PMID 25404849, 2014). "In Cr:ORL SENCAR mice, immunodepletion of either CD4+ or CD8+ T cells was sufficient for efficient infection and papillomatosis, although deletion of one subset did not inhibit the recruitment of the other subset to the infected epithelium." (PMID 25121947, 2014). "Culture fluids of infected NP-2/CD4/CCR5 cells on day-seven, NP-2/CD4/CKR-L3 cells on day-42 and NP-2/CD4/CCR6 cells on day-52 were assayed for RT activities when CPE ascended at the level of 80-90% cell infection." (PMID 24980635, 2014). "Under the formulation of this saturated infection rate, the basic virus reproductive number R0 is independent of the total number of CD4+ T cells." (PMID 24829609, 2014). "Various modes of infection have been proposed, which include transfer through epithelial cells and intestinal epithelium, transport of HIV via DCs present at mucosal surfaces, and direct infection of resident CD4 T cells." (PMID 24995008, 2014). "Primary, but not secondary, Ad5hr inoculation increased the frequency of CXCR3+ CD4+ T cells in blood, while secondary, but not primary, Ad5hr infection transiently increased the frequencies of Ki67+, HLADR+ and CD95+/CCR5+ CD4+ T cells in blood." (PMID 25203111, 2014). "The CD4+ T cell-mediated immune response against influenza plays a role in limiting the severity of infection in the absence of previous antibodies." (PMID 24187568, 2013). "As expected, C57BL/6 mice had increasing numbers of CD4+ and CD8+ T cells that could produce IFN-γ as infection progressed, which paralleled the increasing numbers of T cells within the lung." (PMID 23472214, 2013). "Almost 30 years after its initial discovery, infection with the human immunodeficiency virus-1 (HIV-1) remains incurable and the virus persists due to reservoirs of latently infected CD4+ memory T-cells and sanctuary sites within the infected individual where drug penetration is poor." (PMID 23364195, 2013). "Due to the reciprocal developmental pathway, Th17 cells (CD4+IL-17+) were also analysed, and an increased percentage was seen only at day 28 after infection in B6.CCR7-/- mice (data not shown)." (PMID 24205367, 2013). "Unlike the virological synapse, the infectious synapse does not rely on productive infection of DC, but also allows for viral transmission to target CD4+ T cells." (PMID 23590845, 2013).
infection (continued). "Impaired participants were significantly younger than unimpaired participants (46.5±1.17 years versus 50.8±1.6 years, p = 0.033), but they were not different concerning infection duration, CD4 count, viral load or CDC stage at the time of evaluation." (PMID 23874398, 2013). "The model also suggests that endogenous reactivation occurs via a threshold mechanism with respect to the recruitment rates of CD4+ T cells, with reactivation occurring at the same age regardless of the time of primary infection." (PMID 23580062, 2013). "Herein, we expand on those findings to show protection from infection with HIV-1 pseudovirus representing clade C. In addition, C. crescentus constructs that express the CD4 mimetic CD4M33F23, multiple anti-HIV-1 lectins, as well as three variants of gp41 fusion inhibitors are introduced." (PMID 23840383, 2013). "In the second case, a strictly R5 strain by phenotypic measure and webPSSM, Maraviroc inhibited infection by 3 logs but did not fully inhibit entry in U87.CD4.CCR5 cells." (PMID 23667426, 2013). "Within H. polygyrus-infected WT mice the CD4+Foxp3− Teff-cell population expanded at a slower rate than the CD4+Foxp3+ Treg cells, not increasing significantly until day 14 of infection." (PMID 23319295, 2013). "We observed a significant population of IL-13+ CD4+ T-cells within the intestinal lamina propria early during infection in Itgb8 (CD11c-Cre) which was not apparent in control mice." (PMID 24098124, 2013). "Our studies appear to indicate that at an early phase of infection NO does not affect the expansion of CD4+CD25+Foxp3+ regulatory T cells." (PMID 23936574, 2013). "Since most CD4+ T cells express relatively low levels of CCR5, this property could impact cell targeting by restricting infection in vivo to the limited subset of cells expressing high levels of CCR5." (PMID 24219995, 2013). "Moreover, CD4+ T cells and CD8+ T cells producing IFN-γ were highly detected in the ears of the SGE-3X mice prior to infection." (PMID 23656976, 2013). "We also observed a slight increase in IFNγ+ lamina propria CD4+ T-cells in Itgb8 (CD11c-Cre) mice early post-infection; however, these levels were not significantly different from those seen in control mice." (PMID 24098124, 2013). "Tetramer staining was specific, as infection with Salmonella Typhimurium did not induce expansion of tetramer-specific CD4 T cells." (PMID 24204262, 2013). "This leads to activation, expansion, and functional maturation of Mtb-specific CD4+ T cells that home to the site of primary infection in lung and activates innate immune cells such as macrophages to release IFN-γ and TNF-α to control infection." (PMID 24109479, 2013). "Six weeks after infection there was still a strong negative correlation between TNF-α+IL-2+ CD4 T cells and the level of bacteria (R2 = 0.92 and 0.57, and p<0.0001 and p = 0.0073 for Ag85B and TB10.4, respectively; fig." (PMID 23977248, 2013). "Reduction of HIV-infection induced by E2 in CD4+ T-cells was not due to CCR5 down-regulation, but was an entry-mediated mechanism since infection with VSV-G pseudotyped HIV was not modified by E2." (PMID 23614015, 2013). "Non-proliferating (SNARFhi) CD4+ T cells that were not productively infected (EGFP−) were sorted 5 days post-infection and lysed for either the detection of HIV DNA by real-time PCR or RNA for microarray studies." (PMID 24339779, 2013). "Strikingly, adoptive transfer of wild-type but not Ifnγ−/− CD4+ T lymphocytes into Cxcr3−/− animals prior to infection corrected the defect in inflammatory macrophage activation, simultaneously reversing the susceptibility phenotype of the knockout animals." (PMID 24130498, 2013). "VACV genes expressed early during infection tend to be preferentially recognized by CD8 T cell responses, while VACV genes expressed at intermediate and/or late times post infection tend to be preferential targets for CD4 T cell and antibody responses." (PMID 23951355, 2013).